HLX (H2.0 like homeobox)
Diseases named in the same sentence as HLX in open-access papers:
HLX is named in the same sentence as 40 diseases in open-access papers, as found by Europe PMC text mining. Sharing a sentence is not in itself a finding about the gene and the disease. The quoted sentences say what the papers report.
acute myeloid leukemia (6 papers, 2018 to 2025). Acute myeloid leukemia (AML) is a group of neoplasms arising from precursor cells committed to the myeloid cell-line differentiation. "HLX has also been implicated in acute myeloid leukemia as a promising prognostic and therapeutic target." (PMID 40003710, 2025). "For other SNPs localized in HLX, the association of some polymorphisms with GD, childhood asthma, and therapy-related acute myeloid leukemia (t-AML) was previously confirmed." (PMID 35336820, 2022). "The H2.0-like homeobox transcription factor (HLX) regulates hematopoietic differentiation and is overexpressed in Acute Myeloid Leukemia (AML), but the mechanisms underlying these functions remain unclear." (PMID 30082823, 2018). "In addition, HLX is highly expressed in acute myeloid leukemia (AML)." (PMID 37719132, 2023). "Aberrant expression of HLX has been found in 87% of acute myeloid leukemia (AML) patients and is correlated with inferior overall survival." (PMID 29581848, 2018). "Aberrant activities of particular NKL homeobox genes have been described in myeloid malignancies as well, exemplified by DLX2, HLX and VENTX in acute myeloid leukemia (AML)." (PMID 31825998, 2019). "To identify genes that are directly regulated by HLX in human hematopoietic cells, we performed ChIP-Seq in two mammalian cell lines (chronic myelogenous leukemia CML: K562 and acute myeloid leukemia-AML HL60) overexpressing a FLAG-tagged version of hHLX." (PMID 30082823, 2018).
asthma (5 papers, 2012 to 2022). "An association with two tagging SNPs, rs3806325 and rs12141189, representing seven HLX polymorphisms, was reported in childhood asthma." (PMID 35336820, 2022). "The top-ranked nominally significant DMP associated with persisting asthma is located in the vicinity of the HLX gene, which has been previously implicated in childhood asthma." (PMID 26691723, 2015). "The top-ranked DMP associated with persisting asthma (cg23603194) is located 8 kb downstream of the transcriptional start site (TSS) of the HLX gene, which has been previously implicated in childhood asthma." (PMID 26691723, 2015). "The top-ranked persistent-asthma-associated DMP (cg23603194) identified in this study is downstream of the HLX gene that has been previously implicated in the pathogenesis of asthma." (PMID 26691723, 2015). "The top-ranked DMP associated with persisting asthma (cg23603194, located downstream of the HLX gene) was consistently hypomethylated in asthma-affected twins compared with their unaffected co-twin (mean Δβ = −0.11, P = 6.87E-06, permuted empirical P = 0.0009)." (PMID 26691723, 2015). "Therefore, the decreased expression of miR-128 and increased expression of its target, the HLX serve as potential therapeutic targets for equine as well as human asthma." (PMID 29231896, 2017). "HLX has been identified as an important regulator of TH1 differentiation and a suppressor of TH2 commitment, mediating pathways that are known to be perturbed in asthma." (PMID 26691723, 2015). "The further follow-up of our cohort will help to elucidate which of these children will also develop atopic diseases and/or asthma and whether the TBX21 and HLX genotypes have an impact on their later immune development." (PMID 22303482, 2012).
diffuse large B-cell lymphoma (5 papers, 2018 to 2023). "For example, in anaplastic large cell lymphoma and diffuse large B-cell lymphoma, the HLX was overexpressed in cancer tissues." (PMID 37719132, 2023). "Analyzing the physiological activity of NKL homeobox genes in B-cell development revealed aberrant expression of HLX (H2.0-like homeobox) in HL, diffuse large B-cell lymphoma (DLBCL), and anaplastic large cell lymphoma (ALCL)." (PMID 35884913, 2022). "In diffuse large B-cell lymphoma, the expression of HLX was regulated by EBV-mediated STAT3 activation, and STAT3 was also confirmed to regulate the expression of HLX in Hodgkin lymphoma." (PMID 37719132, 2023). "Here, we introduce the NKL-code in normal hematopoiesis and focus on deregulated NKL homeobox genes in B-cell lymphoma, including HLX, MSX1 and NKX2-2 in Hodgkin lymphoma; HLX, NKX2-1 and NKX6-3 in diffuse large B-cell lymphoma; and NKX2-3 in splenic marginal zone lymphoma." (PMID 31779217, 2019). "STAT3 has been shown to activate HLX expression in cell lines derived from HL (L-540) and EBV-positive diffuse large B-cell lymphoma (DLBCL, DOHH-2/EBV)." (PMID 32922661, 2020).
anaplastic large cell lymphoma (4 papers, 2020 to 2023). Anaplastic large cell lymphoma (ALCL) is a rare and aggressive peripheral T-cell non-Hodgkin lymphoma, belonging to the group of CD30-positive lymphoproliferative disorders, which affects lymph nodes and extranodal sites. "HLX: H2.0-like homeobox (HLX) is overexpressed in several hematopoietic malignancies including HL, DLBCL and anaplastic large cell lymphoma (ALCL)." (PMID 33921702, 2021).
B-cell lymphoma (3 papers, 2018 to 2019). "Some of these identified genes have been previously shown to be deregulated in subsets of particular B-cell lymphomas, including HLX in HL, MSX1 in MCL, NKX2-1 in DLBCL, and NKX2-3 in SMZL, MALT lymphoma and DLBCL." (PMID 30308041, 2018). "Our data assemble a pathological gene regulatory network surrounding HLX and highlight the NKL homeobox gene subclass in this type of B-cell lymphoma." (PMID 29581848, 2018). "In conclusion, our study highlights HLX deregulation in HL subsets, extending the oncogenic potential of NKL homeobox genes in B-cell lymphoma." (PMID 29581848, 2018). "Of note, NKL homeobox genes HLX, NKX2-1, NKX2-3, NKX6-3 and MSX1 are deregulated in B-cell lymphoma and show aberrant activity in T-ALL as well which might indicate similar oncogenic functions in both lineages of lymphoid malignancies." (PMID 29581848, 2018).
colorectal cancer (3 papers, 2023 to 2025). A primary or metastatic malignant neoplasm that affects the colon or rectum. "However, the role of HLX in the carcinogenesis and progression of colorectal cancer (CRC) patients has rarely been reported." (PMID 37719132, 2023). "In colorectal cancer (CRC), HLX acts as a tumor suppressor in the early stages of carcinogenesis but promotes cancer progression in later stages." (PMID 40003710, 2025).
leukemia (3 papers, 2018 to 2025). A malignant (clonal) hematologic disorder, involving hematopoietic stem cells and characterized by the presence of primitive or atypical myeloid or lymphoid cells in the bone marrow and the blood. "Abnormal HLX expression has been linked to autoimmune diseases like Graves’ disease and cancers, including gastric and colon cancers, as well as hematopoietic malignancies such as leukemia." (PMID 40003710, 2025). "Thus, understanding the physiological roles of HLX in hematopoietic development and disease, including leukemia, remains a central issue in HSC biology." (PMID 30082823, 2018). "In addition, the inhibition of HLX expression could reduce the proliferation and clonogenicity of leukemia cells and prolong the survival rate." (PMID 37719132, 2023).
acute appendicitis (2 papers, 2022 to 2023). "In an independent acute appendicitis GWAS performed on the FinnGen cohort, the HLX locus on chromosome 1q41 has reached genome-wide significance (top SNP = rs3738182, p = 7.1 × 10−10)." (PMID 35693796, 2022). "Our results prioritize HLX and CTSB as potential causal genes for appendicitis and suggest a shared genetic mechanism between appendicitis and CRP concentrations." (PMID 35693796, 2022). "The top SNP overlaps a transcription start site of HLX, and the gene is overexpressed in the appendix of appendicitis patients." (PMID 35693796, 2022). "The results of this study prioritize HLX and CTSB as potential causal genes for appendicitis and suggest a shared genetic mechanism between appendicitis and CRP concentrations." (PMID 35693796, 2022). "Moreover, gene expression of HLX is significantly higher in the appendix of appendicitis patients compared to that of individuals who were undergoing intra-abdominal surgery for a non-inflammatory condition (p = 0.008)." (PMID 35693796, 2022). "The expression of HLX is increased in the appendix of appendicitis patients compared to controls." (PMID 35693796, 2022). "Importantly, CRP is known as a potential biomarker for acute appendicitis and its severity in children, yet a study revealed that HLX and CTSB genes are possible etiologies for appendicitis and propose a shared genetic mechanism between appendicitis and CRP levels." (PMID 37873776, 2023).
hepatocellular carcinoma (2 papers, 2018 to 2024). A malignant tumor that arises from hepatocytes. "Moreover, HLX is also considered as a tumor suppressor in hepatocellular carcinoma." (PMID 29945573, 2018).
psoriasis (2 papers, 2022 to 2025). An autoimmune condition characterized by red, well-delineated plaques with silvery scales that are usually on the extensor surfaces and scalp. "Our work proposed that STFs (PPARG, ZFPM2, ZNF415, HLX, and ANHX) mediate the initiation of chronic inflammation and metabolic disorders that increase the risk of developing AD in the psoriasis population." (PMID 35669784, 2022). "PPARG, ZFPM2, ZNF415, and HLX were down-regulated in psoriasis and AD, while ANHX was up-regulated." (PMID 40343299, 2025). "We identified 5 STFs (PPARG, ZFPM2, ZNF415, HLX, and ANHX) in common DEGs and investigated their potential roles in psoriasis and AD." (PMID 35669784, 2022). "ZNF384 is a potential therapeutic target for psoriasis and AD by regulating PPARG, ZNF415, HLX, and ANHX." (PMID 35669784, 2022). "Among these, four genes, PPARG, ZFPM2, ZNF415, and HLX, were down-regulated and ANHX upregulated in psoriasis and AD." (PMID 35669784, 2022). "Additionally, ZNF384 was identified as the key transcription factor that modulates the expression of PPARG, ZNF415, HLX, and ANHX, pointing to its potential as a therapeutic target for psoriasis and AD." (PMID 40343299, 2025). "The STFs (PPARG, ZFPM2, ZNF415, HLX, and ANHX) may increase the morbidity rate of AD in psoriasis by initiating a positive feedback loop of excessive inflammation and metabolic disorders." (PMID 35669784, 2022).
anemia (1 paper, 2022). A reduction in the number of red blood cells, the amount of hemoglobin, and/or the volume of packed red blood cells. "After the adjustment by anemia, the AT heterozygotes in HLX rs868058 were found significantly more often in the women with early-onset FGR, compared to those with late-onset disease, also in the codominant model (OR 2.45 95% CI 1.23–4.90, p = 0.034)." (PMID 35336820, 2022).
colorectal adenoma (1 paper, 2018). An adenoma that arises from the colon or rectum. "Using genome-wide DNA methylation analysis, we identified novel aberrant methylation profiles of genes including HLX, CUX2, MKX, NRG3 and PDGFRA associated with the colorectal adenoma-carcinoma sequence progression." (PMID 29945573, 2018).
COVID-19 (1 paper, 2021). A disease caused by infection with severe acute respiratory syndrome coronavirus 2. "One of these genes is HLX, which is found to be upregulated in healthy patients compared to COVID-19 patients." (PMID 35003208, 2021).
endometriosis (1 paper, 2020). The growth of functional endometrial tissue in anatomic sites outside the uterine body. "miR-20a via ERG/HLX/STAT4/perforin axis could mediate the cytotoxicity of natural killer (NK) cells in endometriosis." (PMID 32850438, 2020).
lymphoma (1 paper, 2019). A malignant (clonal) proliferation of B- lymphocytes or T- lymphocytes which involves the lymph nodes, bone marrow and/or extranodal sites. "Accordingly, expression profiling data of EBV-positive and EBV-negative DLBCL and HL patients showed higher transcript levels of HLX in EBV-positive patients of both lymphoma entities." (PMID 31141539, 2019). "One explanation for this weak association might be that in addition to EBV other oncogenic factors operating in lymphoma cells influence STAT3-signaling and HLX expression as well." (PMID 31141539, 2019).
medulloblastoma (1 paper, 2025). A malignant, invasive embryonal neoplasm arising from the cerebellum. "For example, SE heterogeneity analysis has identified SOX10 as the master regulator of the RTK I subtype in glioblastoma, HLX as the master regulator of the Group 3 subtype in medulloblastoma, and LMX1A as the master regulator of the Group 4 subtype in medulloblastoma." (PMID 40361105, 2025).
metabolic syndrome (1 paper, 2022). A cluster of metabolic risk factors for CARDIOVASCULAR DISEASES and TYPE 2 DIABETES MELLITUS. "ZNF384 is the potential transcription factor that may modulate STFs PPARG, ZNF415, HLX, and ANHX, thus subsequently triggering hyperinflammatory states and metabolic syndromes." (PMID 35669784, 2022).
odontogenic cyst (1 paper, 2025). A cyst in the jaw that arises from tissues of tooth development. "Incorporating Dlx-5 and HLX expression analyses could enhance diagnostic accuracy, guide treatment decisions, and improve prognostic evaluations for patients with odontogenic cysts." (PMID 40003710, 2025). "While studies have primarily focused on HLX’s role in tumor formation, its presence in odontogenic cysts remains unexplored." (PMID 40003710, 2025). "Furthermore, it was considered that the expression of Dlx-5 and HLX might help reveal the behavioral differences between odontogenic cysts." (PMID 40003710, 2025). "Consequently, it is hypothesized that the detection of Dlx-5 and HLX expression in odontogenic cysts may exert a positive influence on treatment planning and prognostic predictions." (PMID 40003710, 2025).
radicular cysts (1 paper, 2025). "Expression: HLX exhibited weak to moderate levels of immunoreactivity in epithelial cells of radicular cysts." (PMID 40003710, 2025).
T-cell lymphomas (1 paper, 2019). "The most widespread overexpressed NKL homeobox genes in T-cell lymphomas were HHEX, HLX, MSX1 and NKX2-3, all members of the NKL-code." (PMID 31143370, 2019).
uveitis (1 paper, 2025). An inflammatory process affecting a part of or the entire uvea. "Overall, our study offers worthy insight into the interconnected molecular pathways of AS and uveitis, and emphasizes the potential of HLX and SLC25A20 as diagnostic markers and targeted treatment approaches for patients suffering from these circumstances." (PMID 40929101, 2025). "Intersection of machine learning results across AS and uveitis cohorts identified HLX and SLC25A20 as core diagnostic biomarkers, with both genes demonstrating significant upregulation in disease groups (p < 0.05)." (PMID 40929101, 2025). "The association of HLX with Th17 cell differentiation indicates a possible link to immune dysregulation, which is a hallmark of both AS and uveitis." (PMID 40929101, 2025). "Parallel analysis in uveitis identified HLX and SLC25A20 as consensus biomarkers across LASSO, SVM-RFE, and Random Forest, validated through multi-algorithm intersection." (PMID 40929101, 2025). "To identify core regulatory genes shared between AS and uveitis, we first intersected genes from WGCNA-derived disease-associated modules and cross-disease DEGs, yielding five candidate genes: SORL1, TLR8, HLX, SLC25A20, and IGSF6." (PMID 40929101, 2025). "Machine learning nominated HLX and SLC25A20 as core biomarkers, demonstrating robust diagnostic accuracy in discovery (AS AUC: 0.688/0.700; uveitis AUC: 0.867/0.838) and validation cohorts (AS AUC: 0.653/0.667; uveitis AUC: 0.662/0.736)." (PMID 40929101, 2025). "The findings from our study highlight the critical role of HLX and SLC25A20 as potential cross-disease biomarkers that bridge AS and uveitis." (PMID 40929101, 2025). "In conclusion, this study successfully identifies HLX and SLC25A20 as core biomarkers linking AS and uveitis." (PMID 40929101, 2025). "HLX and SLC25A20 emerge as immunologic regulators bridging AS and uveitis pathogenesis." (PMID 40929101, 2025).
tumor (8 papers, 2017 to 2025). "The H2.0-like homeobox gene (HLX) encodes transcription factors involved in tumor formation and plays a critical role in cancer development." (PMID 40003710, 2025). "Previous studies have shown that HLX is correlated with the initiation and progression of tumor." (PMID 37719132, 2023). "The same researchers demonstrated that lnc-HLX-2-7 functions as an enhancer to upregulate HLX expression and mediates the formation of a positive feedback loop with MYC, thereby promoting tumor progression." (PMID 39859408, 2025). "In this study, we also found that the HLX expression was increased with tumor stage (stage I–stage III) in CRC, and the high expression of HLX was correlated with poor prognosis of the CRC patients." (PMID 37719132, 2023). "Our study of NKL homeobox genes HHEX and HLX in ALCL documents their impact in (deregulated) cell differentiation: HLX as oncogene and HHEX as tumor suppressor gene." (PMID 32922661, 2020). "Among the top five most hyper-methylated promoters, FGF19 is related to HCC tumor promotion, FGF4 is related to HCC drug response, and HLX is involved in normal liver development." (PMID 28938868, 2017). "Additionally, ATAC peak profiles for target genes in patient recurrent tumor samples, showed proximal gene linkages in clusters mediating the progenitor_photoreceptor signature and cycling progenitors for regulators such as NFE2L2, HLX, HSPH1, and KDM4B." (PMID 39711559, 2024).
cancer (7 papers, 2014 to 2025). A tumor composed of atypical neoplastic, often pleomorphic cells that invade other tissues. "HLX probably played a carcinostasis role in the early stages of CRC but exhibited a cancer-promoting effect in the advanced stages." (PMID 37719132, 2023). "We found that the promoter methylation level of HLX was prominently increased in cancer tissues compared to paracancerous tissues in CRC patients." (PMID 37719132, 2023). "Furthermore, the H2.0-like homeobox gene (HLX) is thought to play a significant role in normal hematopoietic and stem cell proliferation, differentiation, cancer development, and normal tissue maintenance." (PMID 40003710, 2025). "Our study demonstrated that HLX probably exhibits dual roles at different stages of CRC; HLX might play a carcinostasis role in the early stage of CRC, but exhibit cancer-promoting effects in the advanced-stage." (PMID 37719132, 2023). "Furthermore, MIXL1 expression is detected in the cancer genome atlas (TCGA) AML samples in a pattern mutually exclusive from that of HOXA9, CDX2 and HLX suggesting the existence of a core, yet distinct HOX transcriptional program." (PMID 25544748, 2014).
infection (1 paper, 2018). The state of being infected such as from the introduction of a foreign agent such as serum, vaccine, antigenic substance or organism. "In addition, among 46 TRP32 target genes previously found to be differentially expressed during infection, 8 are also TRP47 targets, including CAP1, CMC1, HLX, ING1, MTFR2, NAT10, PARP16, and POLDIP3." (PMID 30408047, 2018).
HLX also shares sentences with these, for which no sentence is quoted: Hodgkins lymphoma (3 papers); childhood asthma (2); splenic marginal zone lymphoma (2); ankylosing spondylitis (1); autoimmune disease (1); brain tumors (1); colon cancers (1); cyst (1); esophageal squamous cell carcinoma (1); Graves disease (1); MALT lymphoma (1); mantle cell lymphoma (1); metabolic disorders (1); oligodendroglioma (1); pancreatic cancer (1); Sepsis (1).